MT3 (metallothionein 3)
Diseases named in the same sentence as MT3 in open-access papers (continued):
Sharing a sentence is not in itself a finding about the gene and the disease.
bladder cancer (6 papers, 2011 to 2024). "Recent studies have suggested that MT3 is an arsenic-upregulated oncogene for the tumor growth and invasion of prostate and bladder carcinoma cells." (PMID 36009228, 2022). "Metallothioneins have been viewed as modulators in a number of biological regulations regarding cancerous development; however, the function of metallothionein 3 (MT3) in bladder cancer is unexplored." (PMID 30813460, 2019). "Although the mechanisms of MT3 in cancer tumorigenesis have not been established clearly, previous studies have suggested that potentially, MT3 can be a tumor marker for early detection of prostate and bladder cancer." (PMID 30813460, 2019). "The results suggested that MT3 is the oncogene in bladder cancer and ectopic overexpression of MT3 enhances tumorigenesis of human bladder carcinoma cells." (PMID 30813460, 2019). "Results of RT-qPCR assays revealed that TSGH-8301 cells had the highest levels of MT3 among the four bladder carcinoma cell lines." (PMID 30813460, 2019). "Ours has been the first study to reveal that arsenic can induce HO-1, NDRG1 and MT3 gene expressions in bladder carcinoma T24 cells." (PMID 30813460, 2019). "In this study, we determined the expressions of MT3 in bladder carcinoma cells and bladder tissues, and examined the regulatory mechanisms and potential function of MT3 in bladder carcinoma cells." (PMID 30813460, 2019). "The experiments indicated that MT3 is an arsenic- and hypoxia-upregulated oncogene that promotes cell growth and invasion of bladder carcinoma cells via downregulation of NDRG1, NDRG2, and MASPIN expressions." (PMID 30813460, 2019). "The present study has been the first to indicate that upregulation of MT3 by hypoxia in human bladder carcinoma cells is dependent on HIF-1α and HIF-2α, which are well-known to be overexpressed in bladder cancer in vivo." (PMID 30813460, 2019). "A human MT3 expression vector was transfected into bladder carcinoma HT1376 cells to investigate the role of MT3 in proliferation and invasion." (PMID 30813460, 2019). "Metallothionein-3 (MT-3) has been shown to be expressed in several malignancies and to have an impact on patients’ survival in breast and urinary bladder cancer cases." (PMID 25015776, 2015). "The MT-3 isoform which was originally reported as specific to brain has been demonstrated in normal human kidney, renal carcinoma, bladder cancer and prostatic adenocarcinoma." (PMID 21599891, 2011). "Results of 3H-thymidine incorporation assays, Matrigel invasion assays, and xenografts in mice showed that mock-transfected bladder carcinoma cells grew slower in vitro and in vivo than the MT3-overexpressed bladder carcinoma cells, whereas MT3-knockdown attenuated cell invasion of TSGH-8301 cells." (PMID 30813460, 2019). "Our findings indicated that MT3 affects cell proliferation and invasion in bladder carcinoma cells." (PMID 30813460, 2019). "Our results demonstrated that MT3 might be involved in the protection against arsenic toxicity in bladder carcinoma cells." (PMID 30813460, 2019). "The downregulation of NDRG1, NDRG2, and MASPIN gene expressions could account for the enhancement of proliferative and invasive functions of MT3 in bladder carcinoma cells." (PMID 30813460, 2019). "Our results suggest that decreased expressions of NDRG1, NDRG2, and MASPIN genes may account for the increased cell proliferation and invasiveness in bladder carcinoma cells with MT3 stably overexpressed." (PMID 30813460, 2019). "We determined the regulatory mechanisms and potential function of MT3 in bladder carcinoma cells." (PMID 30813460, 2019). "It was found that MT3 might also participate in the protection against arsenic toxicity in bladder carcinoma cells." (PMID 30813460, 2019). "Ectopic overexpression of MT3 enhanced tumorigenesis of bladder carcinoma T24 cells in vivo." (PMID 30813460, 2019).
bladder cancer (continued). "Urinary cytology demonstrated the presence of MT-3 positive cells in the urine of some bladder cancers but did not correlate with active disease status." (PMID 21303554, 2011). "This would explain the presence of MT-3 positive cells in the urine from individuals negative for a recurrence of bladder cancer when examined by cytoscopy." (PMID 21303554, 2011). "The expression of the MT-3 isoform in cancerous bladder tissues which was absent in normal bladder tissues, and suggested its use as a potential biomarker for bladder cancer." (PMID 21599891, 2011). "A prior study suggested that MT3 might be an effective biomarker for bladder cancer although the biologic functions of MT3 have not been fully understood." (PMID 30813460, 2019). "However, the effects of MT3 on the expressions of NDRG family genes in bladder carcinoma cells have not been evaluated yet." (PMID 30813460, 2019).
glioma (6 papers, 2015 to 2024). A benign or malignant brain and spinal cord tumor that arises from glial cells (astrocytes, oligodendrocytes, ependymal cells). "Further studies will be needed to elucidate the comprehensive mechanisms underlying the cytoprotective effect of MT3 on glioma resistance." (PMID 32029749, 2020). "Consistent with the result showing that MT3 knockdown induced arrested autophagy in GL261 glioma cells, following irradiation MT3 deficient glioma cells exhibited lysosomal pH shifting toward more alkaline direction as compared with that in Negative control transfected cells." (PMID 32029749, 2020). "On the contrary, relatively little is known regarding the role of MT3, a CNS-enriched Mt isoform, in cancers including glioma." (PMID 32029749, 2020). "As MT3 plays a role in autophagy in astrocytes, here, we investigated its role in irradiated glioma cells." (PMID 32029749, 2020). "Similar to the findings obtained in primary astrocytes, in the present study, siRNA knockdown of MT3 in GL261 glioma cells induced arrested autophagy following irradiation, likely due to impaired lysosomal degradation." (PMID 32029749, 2020). "Knockdown of MT3 with siRNA in irradiated glioma cells induced arrested autophagy, and decreased cell survival." (PMID 32029749, 2020). "In summary, we demonstrated the roles of MT3 and zinc in radiation-induced autophagy and radioresistance in glioma cells." (PMID 32029749, 2020). "Subsequent survival analysis demonstrated that MT3 knockdown decreased the survival of GL261 glioma cells after irradiation." (PMID 32029749, 2020). "MT3 appears to be a key regulator for autophagy flux via zinc-dependent lysosomal acidification, and hence contributes to resistance of glioma cells to irradiation treatment." (PMID 32029749, 2020). "The analysis of MT1A, MT1E, MT1X, MT2, MT3 gene mRNA expression was determined in n = 51, n = 53, n = 49, n = 55, n = 51 glioma patients respectively." (PMID 30932010, 2019). "Quantification of MT3 expression in normal astrocytes, U251 and U87 glioma cell lines revealed that MT3 is elevated more than 4 fold in U87 cells, compared to normal astrocytes." (PMID 26493598, 2015). "Based on these findings, we hypothesized that glioma cells, as a cancerous counterpart of glial cells of developing brains, might utilize this novel cellular mechanism involving MT3 and zinc as a route for circumventing the toxicity of IR." (PMID 32029749, 2020). "The cytoprotective effect of MT3 in glioma cells has been reported by others." (PMID 32029749, 2020). "Since autophagy flux plays a cytoprotective role in irradiated glioma cells, present results suggest that MT3 and zinc may be regarded as possible therapeutic targets to sensitize glioma cells to ionizing radiation therapy." (PMID 32029749, 2020). "As such, MT3 may prove to be a suitable target in improving the efficacy of irradiation treatment in gliomas." (PMID 32029749, 2020). "Present results further support this idea, and suggest that the strategy aiming at the blockade of lysosomal acidification, especially targeting MT3 and/or zinc, may prove useful to find a supportive measure to current glioma therapy." (PMID 32029749, 2020). "To examine the role of MT3 in GL261 glioma cell line, we downregulated MT3 using siRNA." (PMID 32029749, 2020). "Although, the connection between CNS cancers and MT-3 was already described (e.g. up-regulation and poor survival for glioblastoma multiforme), the primary function of MT-3 and the mechanisms underlying its effect on gene expression in Nbl were not elucidated so far." (PMID 29435113, 2018). "Hence, MT3 may contribute to glioma survival through diverse ways including increases in autophagy flux through lysosomal acidification." (PMID 32029749, 2020).
glioma (continued). "Therefore, downregulation of MT3 or zinc chelation at the time of irradiation treatment may provide a beneficial effect to glioma patients by blocking the autophagy flux and increasing glioma cell death." (PMID 32029749, 2020). "Here we checked MT1A, MT1E, MT1X, MT2, MT3 gene expression level and epigenetic regulation for one of the highly expressed metallothioneins, MT1A, in different grade gliomas and looked for clinical significance of MT gene activity in glioma tissue in terms of patient survival." (PMID 30932010, 2019).
acute myeloid leukemia (5 papers, 2014 to 2024). Acute myeloid leukemia (AML) is a group of neoplasms arising from precursor cells committed to the myeloid cell-line differentiation. "Moreover, aberrant methylation of hub gene AGR2 was reported to be associated with ovarian cancer, while MT3 was a putative tumor suppressor gene in pediatric acute myeloid leukemia." (PMID 32064261, 2020). "The overexpression of MT3 can inhibit cell proliferation and promote tumor cell apoptosis in pediatric acute myeloid leukemia." (PMID 32328342, 2020).
Obesity (5 papers, 2008 to 2025). Accumulation of substantial excess body fat. "Metallothionein-3 (MT3) is a zinc-binding protein and was observed that in null MT3 male mice there is an increase in weight, resulting in obesity." (PMID 26042666, 2015). "Our findings indicate a previously unknown role of MT3 in the differentiation of 3T3-L1 cells into adipocytes and provide a potential novel target that might facilitate obesity treatment." (PMID 36978888, 2023). "In addition, the observed developed obesity in male MT3-null mice is due likely to abnormal leptin signaling in the hypothalamus." (PMID 28538697, 2017). "Although the WAT samples were obtained from obese subjects, it is unclear whether the presence of MT-3 mRNA is indicative of hypoxia within the tissue in human obesity." (PMID 18206644, 2008). "Our data revealed that MT3 can suppress 3T3-L1 adipocyte differentiation indirectly by inhibiting the transcriptional activity of PPARγ and by reducing ROS levels in the early stages of adipogenesis, thus providing a potential novel target for the prevention and treatment of obesity." (PMID 36978888, 2023). "Furthermore, metallothioneins, particularly MT-3, play a significant role in regulating autophagy and lysosomal functions, especially under conditions of oxidative stress, which is functionally important for Cu/Zn-SOD in the context of obesity." (PMID 40453670, 2025). "However, there are no clear data on how MT3 is engaged in the development of obesity, especially in 3T3-L1 adipocyte differentiation; the underlying molecular pathways remain unclear." (PMID 36978888, 2023).
amyotrophic lateral sclerosis (4 papers, 2010 to 2024). Amyotrophic lateral sclerosis (ALS) is a neurodegenerative disease characterized by progressive muscular paralysis reflecting degeneration of motor neurons in the primary motor cortex, corticospinal tracts, brainstem and spinal cord. "In addition, MT-3 has been associated with neurodegenerative diseases including amyotrophic lateral sclerosis." (PMID 39758530, 2024). "Here, overexpression of MT-3 prevented neuronal death and prolonged the life span of mice modeling amyotrophic lateral sclerosis." (PMID 39758530, 2024). "Altered MT3 expression has been also reported in amyotrophic lateral sclerosis (ALS), Down syndrome, pontosubicular necrosis, Parkinson's disease, meningitis, and Creutzfeld-Jakob disease." (PMID 20974010, 2010).
diabetes (4 papers, 2020 to 2023). "MT3 has now been described as complicatedly associated with a wide range of diseases including cancer, diabetes, retinopathy, and various brain diseases." (PMID 32843100, 2020). "One study has shown that Mt3-KO mice were protected against STZ-induced diabetes and Mt3-KO islets were resistant to STZ and NO toxicity ex vivo." (PMID 33652748, 2021). "Similar results were obtained in studies carried out in an animal model (Mt3+/+ mice) with STZ induced diabetes, where PDE3A was shown to be implicated in apoptosis of pancreatic islet cells in these animals, and the use of cilostazol alleviated diabetes." (PMID 33153226, 2020).
esophageal squamous cell carcinoma (4 papers, 2011 to 2018). Esophageal squamous cell carcinoma (ESCC) is a type of esophageal carcinoma (EC) that can affect any part of the esophagus, but is usually located in the upper or middle third. "In relation to cancer, downregulation of MT3 has been reported as one of 17 changes in gene expression which are associated with metastasis and poor clinical outcome in a range of solid tumors, including gastric cancer and primary esophageal squamous cell carcinoma (SCC)." (PMID 24962166, 2014). "This was supported by the observation that treatment with 5-aza-2'-deoxycytidine, an inhibitor of DNA methylation reduced the degree of methylation and increase the level of MT3 expression, in esophageal SCC cell lines." (PMID 24962166, 2014). "Furthermore, in agreement with reports in esophageal SCC, treatment with 5-Aza, a specific inhibitor of DNA methylation, led to a significant increase in MT3 expression in AML cells (39.8 fold in HL-60 and 26.8 fold in MV4-11; P < 0.05 and P < 0.01, respectively)." (PMID 24962166, 2014).
melanoma (4 papers, 2011 to 2022). A malignant, usually aggressive tumor composed of atypical, neoplastic melanocytes. "In melanoma cell lines originating from advanced primary or metastatic lesions, endogenous MT3-MMP expression was associated with limited collagen-invasive potential." (PMID 22164270, 2011). "MT3-MMP was also upregulated in melanoma metastases to lung (∼4-fold), small intestine (∼6-fold) and in a single tissue sample of brain metastasis (∼4.5-fold)." (PMID 22164270, 2011). "Since MT3-MMP was significantly upregulated in biopsies of human melanoma metastases, these results identify MT3-MMP as a matrix-dependent modifier of the invasive tumor cell functions during melanoma progression." (PMID 22164270, 2011). "Consistent with these proposed pro-metastatic functions, MT3-MMP expression was increased in biopsies of human melanoma metastasis." (PMID 22164270, 2011). "Likewise, stable MT3-MMP knockdown in the MT3-MMP expressing WM165 melanoma cells led to increased cell elongation and invasive sprouting of cell colonies in collagen." (PMID 22164270, 2011). "This hypothesis and the importance of MT3-MMP for fibrin invasion is strongly supported by our finding that silencing endogenous MT3-MMP in two different melanoma cell lines reduced dramatically their ability to invade and form sprouts in 3D fibrin." (PMID 22164270, 2011). "Within these fibrin-rich sites, MT3-MMP-dependent proteolysis could enhance the passage of melanoma cells into lymphatic vessels, where discontinued basement membranes do not form significant barriers for cell invasion." (PMID 22164270, 2011). "As supported by a recent report of Nogo receptor 1 shedding by endogenous MT3-MMP in neurons, MT3-MMP may modulate also melanoma cell invasion by cleaving transmembrane or pericellular proteins." (PMID 22164270, 2011). "MT3-MMP is involved in EMT and neural crest cell migration, cell adhesion and lymphatic invasion in melanoma, and in human astrocytic tumors." (PMID 35453827, 2022). "The chondroitin sulfate chains of CSPG4 have been shown to bind both pro-MMP-2 and MT3-MMP, an MT-MMP that is expressed on vertical growth phase melanoma and is important for melanoma invasion into collagen gels." (PMID 24069584, 2013). "Taken together, these results suggest that MT3-MMP, essential for WM852 and WM165 melanoma cell invasion in fibrin, is a strong negative regulator of melanoma cell invasion within 3D collagen, where it induced adhesive nodular-type growth pattern." (PMID 22164270, 2011). "As the functional contribution of MT3-MMP in melanoma progression has remained undefined, we have here examined its function using gene-silencing and overexpression in different types of melanoma cells." (PMID 22164270, 2011). "In a variety of cells ranging from epithelial cells, macrophages, and CD4+ T cells to cells from tumors, such as myeloma, pancreatic cancer, and melanoma, membrane CD138 is cleaved by different proteinases, such as MMP9, MT1-MMP, MT3-MMP, collagenase, and trypsin." (PMID 34364875, 2021). "Interestingly, MT3-MMP is specifically upregulated in nodular melanoma, the most aggressive melanoma type, comprising about 15% of all melanoma cases." (PMID 22164270, 2011). "By contrast, as a potent fibrinolytic enzyme, MT3-MMP induced efficient invasion of the cells in fibrin, a provisional matrix component frequently found at tumor-host tissue interfaces and perivascular spaces of melanoma." (PMID 22164270, 2011). "In contrast, the MT3-MMP expressing cells grew as either non-invasive sphere-shaped colonies or groups of rounded cells within collagen, suggesting that MT3-MMP could have an effect on melanoma cell invasion." (PMID 22164270, 2011). "Since MT3-MMP had similar effects in the invasive activities of WM852 cells from nodular melanoma metastases and WM165 cells originated from superficially spreading melanoma metastases, we postulate that the protease may play previously unappreciated role in the metastatic process." (PMID 22164270, 2011).
Parkinson disease (4 papers, 2010 to 2024). A progressive degenerative disorder of the central nervous system characterized by loss of dopamine producing neurons in the substantia nigra and the presence of Lewy bodies in the substantia nigra and locus coeruleus. "It has also been reported that the metallothionein-3 (MT3) level decreases in astrocytes in lesioned areas of degenerative diseases such as Parkinson's disease, amyothrophic lateral sclerosis, and progressive supranuclear palsy." (PMID 20490351, 2010).
amyloid (3 papers, 2016 to 2025). "MT3 levels are reduced in AD brains, but little is known about this protein’s role in amyloid pathology." (PMID 37710351, 2023).
astrocytomas (3 papers, 2019 to 2023). "MT1A, MT1E, MT1X, MT2, MT3 gene expression was elevated in grade IV astrocytomas (glioblastomas) as compared to astrocytomas grade I-III." (PMID 30932010, 2019). "Some studies have shown that MT3 is highly expressed in malignant astrocytoma cells." (PMID 38041044, 2023). "Analysis showed the trend for increasing MT1A, MT1E, MT1X, MT2 and MT3 gene expression in higher malignancy tumours, e.g. glioblastomas as compared to I-III grade astrocytomas." (PMID 30932010, 2019).
glioblastoma (3 papers, 2018 to 2020). The most malignant astrocytic tumor (WHO grade IV). "However, only MT1A and MT2 expression reached a statistically significant level (Mann-Whitney test, p < 0.05), while MT1E and MT3 genes showed the tendency of higher expression in glioblastomas (Mann-Whitney test, p = 0.120, p = 0.058 respectively)." (PMID 30932010, 2019).